NGF (nerve growth factor)
Diseases named in the same sentence as NGF in open-access papers (continued):
Sharing a sentence is not in itself a finding about the gene and the disease.
tumor (continued). "During the development of neurologic tumours or PNI in some nonneurologic tumours, the NGF/TrkA/STAT3 axis significantly facilitates the epithelial‒mesenchymal transition (EMT) of malignant cells." (PMID 40783715, 2025). "The high expression of LEP, NGF and PCOLCE2 in tumor tissues was verified by COAD clinical samples." (PMID 38694509, 2024). "Unfortunately, only two clusters of tumor cells (cluster 3 and cluster 7, which were from adjacent tumor tissues) successfully secreted NGF individually, while tumor cells in clusters 5, 8, 10, and 11 (tumor tissues) failed to secrete NGF." (PMID 38204220, 2024). "NGF‐NGFR communication inefficiency suppressed mitotic spindle formation via HDAC1 unclear trans‐localization‐inhibited PREX1 expression, thereby suppressing the proliferation of T cells that had infiltrated into the tumor tissues of HCC patients." (PMID 38204220, 2024). "NGF can modulate the production of cytokines and chemokines in the TME, influencing the function of immune cells, creating an immunosuppressive milieu, and favoring tumor growth and immune escape." (PMID 38392180, 2024). "NGF can influence the TME, affecting the interactions between cancer cells and surrounding stromal cells, immune cells, and other components, contributing to both tumor growth and suppression." (PMID 38392180, 2024). "On one hand, NGF can induce apoptosis in some cancer cells, limiting their survival, and may modulate immune responses within the TME, influencing the anti-tumor immune response." (PMID 38392180, 2024). "Interestingly, NGF‐NGFR communication and PD‐1 mAb acted synergistically to provide anti‐tumor immunotherapy." (PMID 38204220, 2024). "Furthermore, NGF may indirectly induce the expression of immune checkpoint molecules such as the programmed death-1 ligand (PD-L1), a co-inhibitory factor of the immune response, on tumor cells or immune cells within the TME, further inhibiting the activity of cytotoxic T cells." (PMID 38392180, 2024). "However, expressions of NGF and NGFR are low in tumor tissues, which is responsible for the invasive clinicopathological features and the disappointing prognosis in HCC patients." (PMID 38204220, 2024). "Targeting NGF inhibition in OSCC will reduce nociception, cachexia, and tumor advancement." (PMID 39099944, 2024). "Unfortunately, the expressions of NGF and NGFR were low in the tumor tissues of HCC patients, which could be the possible reason for the reduced numbers of T cells in these tissues." (PMID 38204220, 2024). "Recent studies have shown that mast cells infiltrate tumors and tumor microenvironments and release many mediators (e.g., EGF, NGF, PDGF, SCF, angiopoietin, heparin, IL-8, and VEGF), thereby affecting tumor development, tissue remodeling, and tumor-adaptive immune responses." (PMID 39734347, 2024). "Importantly, the NGF secreted from tumor cells was received mainly by the NGFR expressed in T cells, and this NGF‐NGFR interaction contributed to the primary NGF‐NGFR communication signaling pathway network." (PMID 38204220, 2024). "Importantly, in the NGF‐NGFR communication, NGF was secreted from tumor cells while NGFR was expressed in the T cells." (PMID 38204220, 2024). "The tumor-invading sensory neurons express more CGRP and Trka, the receptor for NGF." (PMID 37371563, 2023). "NGF has been shown to promote angiogenesis by increasing VEGF secretion in cancer cells and targeting NGF through anti-NGF antibodies or small interfering RNA therapies that inhibit tumor angiogenesis." (PMID 37047688, 2023). "Macrophage-derived IL-1β induces non-neuronal cells to synthesize NGF, and tumor cells can also secrete NGF and BDNF to active their Trk receptors to stimulate nerve growth." (PMID 36900158, 2023). "Currently, while a felinized anti-nerve growth factor mAb (frunevetmab) is registered for the treatment of osteoarthritic pain in cats, no felinized anti-tumor mAbs are commercially available." (PMID 37835664, 2023).
tumor (continued). "p75NTR has been shown to exert anti-apoptotic functions, possibly upon stimulation by the precursor form of NGF (proNGF), in tumor growth and spreading, which is largely independent of the mitogenic NGF/TrkA pathway." (PMID 35681602, 2022). "No significant variation in the NGF levels were observed in the entire cohort of tumor samples or in the two subgroups compared to the controls." (PMID 36142158, 2022). "Neurotrophic factors such as nerve growth factor (NGF), and brain-derived neurotrophic factor (BDNF), are considered drivers of neurogenesis during development and regeneration, playing a key role in the crosstalk between tumor cells and nerves." (PMID 36406133, 2022). "When serine is lacking, tumor cells can secrete NGF and act on nerve cells to increase the secretion of serine." (PMID 35126957, 2022). "The tumor microenvironment also includes immunologically active neuropeptides/neuromediators such as calcitonin gene-related peptide (CGRP), substance P, neurotensin, and nerve growth factor (NGF)." (PMID 35565462, 2022). "In particular, it was reported that nerve growth factor (NGF) and brain-derived neurotrophic factor (BDNF) could stimulate tumor cell proliferation, survival, migration, and/or invasion and was beneficial to tumor angiogenesis." (PMID 35833114, 2022). "Besides, the expression of VEGF (Mhigh/Mlow = 1.48 fold, p-Value = 0.021), NGF (Mhigh/Mlow = 1.79 fold, p-Value = 0.005), and IGF2 (Mhigh/Mlow = 2.12 fold, p-Value = 0.014), which were involved in tumor metastasis were also increased in the Mhigh group." (PMID 35740540, 2022). "Similarly, a recent study on PDAC revealed that sympathetic neuron-mediated catecholamine signaling leads to increased NGF expression in PDAC cells, which, in turn, fosters both tumor proliferation (via autocrine signaling) and axonogenesis in vivo." (PMID 34503281, 2021). "Not by chance, the production of NGF, responsible for innervating the tumor masses, is scarcely affected by the lack of serine." (PMID 34207731, 2021). "Second-generation MFC and NGF have demonstrated a good correlation when tumor burden is relatively high (PR, VGPR, CR), but approximately 25% of patients with MRD-negative status by conventional MFC became MRD-positive when they were assessed by NGF." (PMID 35096603, 2021). "In addition, LOXO-101 (a Trk-NGF inhibitor) can reduce innervation and decrease PDAC tumor burden in an orthotopic model." (PMID 34671554, 2021). "Single studies concerning various cancers showed that Pro-NGF/NGF (nerve growth factor), BDNF (brain-derived neurotrophic factor), Ephrin B1, neuroligin-3, pleiotrophin, semaphorin 4F were involved in the regulation of tumor innervation." (PMID 34277455, 2021). "An interesting point is that metformin blocks the tumour-promoting effects of NGF, but these apparently do not depend on decreased AKT signalling." (PMID 33081077, 2020). "The release of neurotransmitters—such as catecholamines and acetylcholine—by nerves into the vicinity of cancer and stromal cells, along with the secretion of neurotrophic growth factors such as NGF and BDNF, and miRNAs by cancer cells, drives the crosstalk that ultimately enables tumor progression." (PMID 33322770, 2020). "Both NGF and BDNF have already been shown to promote tumor innervation in other tissues." (PMID 32155948, 2020). "Both VEGFA and NGF promote MMP production facilitating tumor invasion and cancer angiogenesis." (PMID 33324652, 2020). "Similarly, the inhibition of NGF/TrkA signaling in PDAC with a pan-Trk inhibitor blocks NGF-dependent growth of murine PDAC cells, inhibits tumor growth, and increases the efficiency of chemotherapy." (PMID 30741921, 2019). "Studies have shown that several types of cancer overexpress neurotrophins such as NGF and BDNF, which might contribute to tumor progression and angiogenesis." (PMID 31608227, 2019).
tumor (continued). "Increasing bortezomib treatment to further suppress MM disease resulted in a greater reduction in tumour burden, but still no suppression of serum NGF." (PMID 31578352, 2019). "In addition, high adrenergic catecholamines levels promote NGF and BDNF secretion favoring tumor innervation, ensuing further adrenergic signaling in a feed forward loop that promotes tumor growth." (PMID 31248001, 2019). "CXCR4 promotes tumor cell migration toward nerve cells and SDF1 increases NGF expression." (PMID 31921628, 2019). "Additionally, the neurotrophin nerve growth factor (NGF) is a ligand for tropomyosin receptor kinase A (TrkA), which is over-expressed on multiple tumor types." (PMID 30400835, 2018). "Looking over the results of transcriptome analysis we found that most of the tumor-promoting growth factors, such as epidermal growth factor (EGF), hepatocyte growth factor (HGF), nerve growth factor (NGF) or interleukin 6 (IL-6) were expressed at similar level in ASC.B6 and vASC." (PMID 30185144, 2018). "NGF and HO1 were primarily expressed in the cytoplasm of tumor cells." (PMID 28679437, 2017). "The GNC–siRNA group efficiently inhibited the expression of NGF protein in orthotopic tumours, but free siRNA did not significantly reduce the NGF protein expression in tumours." (PMID 28440296, 2017). "Even in the cases where NGF or HO1 were expressed in tumor cells, the non-neoplastic stromal cells did not express NGF or HO1." (PMID 28679437, 2017). "NGF, CVF and ketoprofen reduced the tumor volume by approximately 72%, 68% and 30%, respectively." (PMID 28878143, 2017). "S1P derived from dying tumor cells promoted the shuttling of the nerve growth factor (NGF) receptor tropomyosin receptor kinase A (TRKA) from intracellular vesicles to the plasma membrane, where constitutively produced NGF activated AKT." (PMID 28848247, 2017). "In addition, to investigate the effect of NGF and TRPV1 on the tumor model, the mixture of AsPc-1 cells and PSCs was co-injected into the pancreases of mice." (PMID 26934446, 2016). "In contrast, the combination of NGF plus TRAIL did not reduce the number of tumour spheroids formed by NT SH-SY5Y or pcDNA SH-SY5Y cells." (PMID 27551499, 2016). "Mast cells can exert pro-tumorigenic effects by secreting factors like VEGF, angiopoietin-1, CXCL1, and IL-8 that promote tumor angiogenesis, as well as growth factors such as PDGF, NGF, SCF, FGF2, and proteases that facilitate tumor cell growth and metastases." (PMID 24455486, 2014). "The patients with tumors expressing NGF had the shortest survival and the patients with tumor, which did not express NGF or HO1 showed the longest survival time." (PMID 24180625, 2013). "Nerve growth factor (NGF) was the first discovered member of the neurotrophic factor family; this family is widely expressed in tumor tissues, and is involved in tumorigenesis and tumor growth." (PMID 20219134, 2010). "Furthermore, NGF indirectly supports angiogenesis by upregulating vascular endothelial growth factor (VEGF), which contributes to tumor vascularization and sustains the growing tumor’s metabolic demands." (PMID 41009819, 2025). "Cancer cells release neurotrophins like Nerve Growth Factor (NGF), Brain-Derived Neurotrophic Factor (BDNF), Glial Cell Line-Derived Neurotrophic Factor (GDNF), and artemin (ARTN), which bind to receptors on nerve cells, promoting neurite outgrowth toward the tumor." (PMID 40909268, 2025). "Using a mouse model of prostate cancer-induced bone pain, the anti-NGF was administered both early, starting on day 14 after tumor injection, when nerve sprouting had not yet occurred, and late, starting on day 35, when extensive nerve sprouting had already occurred." (PMID 41301953, 2025).
tumor (continued). "Transcriptomic profiling revealed that KPC organoids upregulated neurotrophic factors (NGF and glial cell line-derived neurotrophic factor (GDNF)) and axon guidance molecules (semaphorin 3A and Ephrin type A receptor 4 (EPHA 4)), implicating tumor-secreted signals in neural remodeling." (PMID 40243726, 2025). "Also, BDNF, GDNF, NGF, and axon guidance molecules, such as CX3CL1, EphA2, CCL2, Slit, and so forth, are groups of neuroactive chemicals generated by the nerves involved in tumor–nerve interaction." (PMID 39346791, 2024). "Collectively, NGF levels were significantly elevated in NSCLC cells compared to normal lung epithelial cells, and their interaction with TrkA receptors in PC12 cells enhanced axonal growth and differentiation, promoting tumor growth in a murine model and augmenting neurotrophic activity." (PMID 39385213, 2024). "Therefore, NGF‐NGFR communication and the immune checkpoint blocker PD‐1 mAb could exhibit a synergistic effect in the tumor suppression procedure." (PMID 38204220, 2024). "NGF released by cancer cells can be a driver of tumor neurogenesis and nerves infiltrated in TME release neurotransmitters, which might stimulate the growth and sustainment of tumor cells." (PMID 36941697, 2023). "In addition, it effectively downregulates the expression of NGF and significantly inhibits tumor progression in pancreatic tumor models without significant adverse effects." (PMID 35127533, 2021). "This group comprises nerve growth factor (NGF), transforming growth factor (TGF)‐β family, platelet‐derived growth factor (PDGF), and interleukin (IL)‐17 family, which has attracted much interest for being involved in regulation of tumor development, invasion, and metastasis." (PMID 34128588, 2021). "The inhibition of NGF signaling inhibits the formation of innervations responsible for the release of serine even if it is not clear what the real source of NGF is within the tumor mass." (PMID 34207731, 2021). "Because EOC cells overexpress NGF/TRKA, which act as proliferative and pro-angiogenic mediators, these results suggest that inhibition of the COX-2/PGE2 axis represents an attractive therapeutic approach to prevent angiogenesis and therefore tumor growth in EOC." (PMID 31817839, 2019). "Furthermore, PaCa-derived NGF attracts Schwann cells via NGFR/p75NTR, which might be interpreted as the recruitment of nerve cells toward the tumor being the first step in PNI." (PMID 31921628, 2019). "NGF stimulates cell proliferation in tumor, but not in normal cells." (PMID 29565967, 2018). "Nerves in the tumor microenvironment were negative for TrkA, NGF, proNGF, p75NTR and sortilin." (PMID 29802376, 2018). "One explanation may be that NGF is different from VEGF or that our study used non-excitable (tumor) cells." (PMID 30483120, 2018). "The free siRNA did not induce a significant decrease of NGF protein expression in tumour tissues." (PMID 28440296, 2017). "In turn, the antitumor activity of CVF and ketoprofen, but not NGF, is possibly associated with a decrease in the level of serum TGF-β1, which directs the cells of the tumor microenvironment to the pro-tumor phenotype, and negatively regulates the cytotoxic function of immune cells." (PMID 28878143, 2017). "In addition, we investigated the effect of NGF and TRPV1 on the tumor model." (PMID 26934446, 2016). "NGF is released in the bloodstream of mammalians (human included) and is critically involved in the protection of several neuronal and non-neuronal cell types, including healthy and tumor cells." (PMID 27439311, 2016). "At the same time, however, as reported for other tumor models, overactivation of the MAPK pathway in MM cells can induce a feedback protective effect against oncogenic growth, while the ATK pathway is mainly involved in stimulating proliferation downstream to NGF-TrkA signaling." (PMID 26496938, 2015).
tumor (continued). "The lack of let-7e may release NGF deprivation and therefore inhibit apoptosis, leading to tumor aggression and HCC metastasis." (PMID 23282077, 2012). "Moreover, blocking NGF can inhibit tumour growth and metastasis, suggesting a key role for NGF in controlling the growth of cancer but not of normal cells." (PMID 21241485, 2011). "Macrophage-derived IL-1β induces non-neuronal cells to synthesize nerve growth factor (NGF), and activated macrophages can also release glial cell-derived neurotrophic factor (GDNF)-activated RET receptors to trigger tumor cell migration." (PMID 36900158, 2023). "Frequency of nerve growth factor and tyrosine kinase A overexpression were significantly higher in the tumours with PNI compared to the tumours without PNI." (PMID 35681586, 2022). "Although high TrkA protein expression was not correlated with PNI status, high NGF protein expression significantly correlated with PNI (p = 0.0024), larger tumor size (p = 0.0172), and higher pathological grade (p = 0.0227)." (PMID 34885121, 2021). "Mechanistically, SNS nerve fiber-secreted norepinephrine promotes never growth factor (NGF) secretion of tumor cells, which in turn recruits SNS never fibers to tumor cells, and ultimately leads to tumorigenesis." (PMID 33390926, 2020). "In addition, NGF/TRKA stimulates cellular proliferation of EOC cells, by the activation of MAPK/ERK and AKT pathways, increasing Bcl2/Bax ratio and c-Myc, indicating the importance of NGF/ TRKA in EOC progression and suggesting that they could be considered as a potential tumor markers." (PMID 31608227, 2019). "The patients with tumors expressing NGF had the shortest OS and RFS; furthermore, the patients with tumor which did not express NGF or HO1 showed the longest survival time." (PMID 24180625, 2013). "Tumor height was correlated with cytokines such as interleukin-8 (IL-8), M-CSF, and stem cell growth factor-beta (SCGF-β), while tumor diameter showed negative correlations with beta-nerve growth factor (β-NGF) and tumor necrosis factor-beta (TNF-β)." (PMID 41048959, 2025). "The results above indicate that whether or not the cells respond to NGF and PlGF-1 may be used as markers to differentiate the two PDX cell lines and likely also other SHH and group 3-derived MB tumour cells." (PMID 26486848, 2015). "Moreover, as these tissue arrays do not provide information about neoadjuvant treatment, chemotherapy and radiotherapy, we could not perform a detailed analysis on NGF and MMP-2 levels in relation to the tumor stage." (PMID 34283074, 2021).